HAPSTR2 (HUWE1 associated protein modifying stress responses 2)
Description:
Together with HAPSTR1 plays a central regulatory role in the cellular response to molecular stressors, such as DNA damage, nutrient scarcity, and protein misfolding. Regulates these multiple stress response signaling pathways by stabilizing HAPSTR1, but also independently of HAPSTR1.
Gene: Protein-coding gene on chromosome X (140,091,678 to 140,092,911, forward strand). Ensembl gene ENSG00000230707.
Subcellular location: Nucleus
Gene Ontology:
Molecular function: protein binding; ubiquitin protein ligase binding
Biological process: protein stabilization
Cellular component: nucleus
Homologues: Orthologues: chimpanzee HAPSTR2 (99% identical), pig HAPSTR2 (86% identical), rabbit HAPSTR2 (84% identical), rat Hapstr2 (82% identical), mouse Gm715 (79% identical), tropical clawed frog hapstr1 (67% identical), zebrafish hapstr1a (63% identical), Drosophila melanogaster CG4768 (29% identical), Caenorhabditis elegans haps-1 (22% identical). Paralogues in human: HAPSTR1 (69% identical).
Diseases named in the same sentence as HAPSTR2 in open-access papers:
HAPSTR2 is named in the same sentence as 5 diseases in open-access papers, as found by Europe PMC text mining. Sharing a sentence is not in itself a finding about the gene and the disease. The quoted sentences say what the papers report.
lung carcinoma (1 paper, 2023). "HAPSTR2-expressing subsets of bone and lung cancer were characterized by striking overexpression of genes involved in neural linage determination." (PMID 36631436, 2023). "To further test whether HAPSTR2 functionally buffers HAPSTR1 loss, we investigated neural-like lung cancer cells, H661, which natively express both HAPSTR1 and HAPSTR2." (PMID 36631436, 2023).
ovarian carcinoma (1 paper, 2023). A malignant neoplasm originating from the surface ovarian epithelium. "Neurogenesis genes also delineated HAPSTR2-high vs. -low brain and ovarian cancer cell lines, altogether consistent with our observations that neural lineage factors likely drive HAPSTR2 expression." (PMID 36631436, 2023).
cancer (1 paper, 2023). A tumor composed of atypical neoplastic, often pleomorphic cells that invade other tissues. "HAPSTR2, expressed primarily in neural and germline tissues and a subset of cancers, retains established biochemical features of HAPSTR1 to achieve two functions." (PMID 36631436, 2023). "HAPSTR2 is expressed primarily in neural and germline tissues, as well as neural, germline, and neural-like cancers." (PMID 36631436, 2023). "Residual expression of HAPSTR2 in some neural or germline cancers (and de novo expression in neural-like subsets of other cancers) also underscores a need to consider paralog effects in future studies of HAPSTR1 in cancer." (PMID 36631436, 2023). "Given the apparent importance of HAPSTR1 in cancer, we also investigated HAPSTR2 expression in tumors and cancer cell lines." (PMID 36631436, 2023). "To better understand the contexts in which cancer cells express HAPSTR2, we investigated genes differentially expressed in HAPSTR2-positive vs. HAPSTR2-negative cancer cell lines from a given lineage." (PMID 36631436, 2023). "Cancer cell lines similarly recapitulated tissue biases in HAPSTR2 expression." (PMID 36631436, 2023). "Yet, we were intrigued to observe HAPSTR2 expression in a subset of cancers from tissues which do not normally express HAPSTR2." (PMID 36631436, 2023). "Together, our data suggest that HAPSTR2 inserted into the genome absent its parental gene’s promoter, where subsequent evolutionary refinement of a proto-promoter resulted in transcription in neural and germline tissues and a subset of cancers." (PMID 36631436, 2023).
Tumor (1 paper, 2023). "Tumor HAPSTR2 was typically low relative to HAPSTR1, but a notable subset of tumors expressed comparable amounts of both paralogs." (PMID 36631436, 2023).
HAPSTR2 also shares sentences with these, for which no sentence is quoted: neurodevelopmental disorder (1 paper).